CD4 (CD4 molecule)
Diseases named in the same sentence as CD4 in open-access papers (continued):
Sharing a sentence is not in itself a finding about the gene and the disease.
autoimmune disease (continued). "Abnormalities in T cells have frequently been reported in autoimmune diseases such as rheumatoid arthritis (RA), systemic lupus erythematosus (SLE), and multiple sclerosis (MS), which is characterized by exaggerated activation of CD4+ T cells." (PMID 29410624, 2018). "The known biological roles and the pro-inflammatory activities of IL-23 in inflammation and autoimmune diseases include but not limit to the induction of Th17-induced secretion of IL-17 and suppression of CD4+CD25+ regulatory T cells." (PMID 29508278, 2018). "In conclusion, we have provided evidence that RFX1 downregulation contributes to the increased IL-17A expression and Th17 cell differentiation in the CD4+ T cells of patients with SLE, as well as promotes the pathologic changes of autoimmune diseases including EAE and lupus-like mice models." (PMID 29422534, 2018). "Thus, in autoimmune disease and in vitro cell culture assays, BACH2 promotes development of a regulatory CD4+ T cell phenotype, while suppressing development of effector CD4+ T cells through both cell intrinsic and extrinsic mechanisms." (PMID 30459773, 2018). "Those patients with a low CD4+ T and low CD4/CD8 ratio are prone to opportunistic infections, splenomegaly, granulomatous disease, lymphoma, gastrointestinal disease, bronchiectasis, and autoimmune disease." (PMID 29849668, 2018). "Adoptive transfer of CD4+CD25+FOXP3+ regulatory T cells (Treg cells) has been successfully utilized to treat graft versus host disease and represents a promising strategy for the treatment of autoimmune diseases and transplant rejection." (PMID 28746369, 2017). "CD4+CD25+ Treg cells contribute to immunological hyporesponsiveness and immune suppression, and therefore, these cells are involved in the maintenance of immune homeostasis and prevent the occurrence of autoimmune diseases." (PMID 28796055, 2017). "p21 also decreased CD4+ and CD8+lpr T cell hyperproliferation and autoimmune disease development." (PMID 28344578, 2017). "Qa-1-restricted CD8+ Tregs have primarily been studied in the context of autoimmune diseases such as EAE and systemic lupus erythematosus, where these CD8+ Tregs suppress autoreactive CD4+ T cells in an antigen-specific manner and protect against disease progression." (PMID 28475642, 2017). "In 1986, Mossman and Coffman presented the concept of distinct T helper cell subsets and MS was later considered a CD4+ Th1-mediated autoimmune disease but not surprisingly the T-cell biology in vivo is more complex than a simple dichotomy." (PMID 28754092, 2017). "It will be important to investigate and understand the mechanisms of differentiation and function of CD4 CTL, particularly for promoting antiviral and antitumor immunity for host protection, as well as for effective intervention and therapy for autoimmune diseases." (PMID 28280496, 2017). "Thymic-derived and peripherally induced CD4+CD25+FoxP3+ Tregs are critical immune regulators to prevent autoimmune disease and for tolerance to “non-self” antigens." (PMID 29225598, 2017). "Although the role of CD8+ T cells in autoimmune diseases is not as well characterized as the role of CD4+ T cells, various studies indicate that they play a role in disease pathogenesis." (PMID 28163705, 2016). "Indeed, IL-15 can be produced by macrophage/monocytes, activated NK cells, CD4+ T cells, and B cells, and involved in the pathogenesis of SLE and other autoimmune diseases." (PMID 27412348, 2016). "In fact, several reports have shown that the presence of activated CD4-Tregs play a critical role in controlling undesired immune responses to self and non-self-antigens, to prevent autoimmune diseases and to achieve peripheral allograft tolerance." (PMID 27245075, 2016). "Our flow cytometric analysis revealed that CD4+RORγt+ Th17 cell frequencies were up to 30% in the kidney of ANCA-GN patients, which is higher than the reported frequencies in most other tissues affected by autoimmune diseases." (PMID 27851911, 2016).
autoimmune disease (continued). "CD4+CD25+ Tregs account for 5–10 % of the CD4+ T cell panel in healthy human and mice, which are sufficient to play an important role in the maintenance of immune homeostasis and the limitation of autoimmune disease." (PMID 26822150, 2016). "CD4+/FOXP3+ Tregs are a subset of suppressive T cells that are crucial to the development and maintenance of self-tolerance that have been shown to prevent autoimmune disease." (PMID 27310015, 2016). "Based on the important role of IL-37 in the suppressive activity of CD4+CD25+ Tregs, it may be feasible to use IL-37 as an immunotherapy for autoimmune diseases, allergies, allograft rejection or even sepsis." (PMID 27941849, 2016). "CD4+FOXP3+ regulatory T cells (Tregs) are a subset of CD4 T cells that play an essential role in maintaining peripheral immune tolerance, controlling acute and chronic inflammation, allergy, autoimmune diseases, and anti-cancer immune responses." (PMID 26623425, 2015). "Thus, 1,25(OH)2D3 administration impaired the induction of CNS autoimmune disease in this model, likely by limiting the access of MBP-reactive CD4+ T cells to the CNS." (PMID 26635791, 2015). "When CD4+CD25− cells, from BALB/c nu/+ mice were transferred into BALB/b nu/nu mice they induced a widespread autoimmune disease that could be prevented by co-transfer of donor CD4+CD25+ cells." (PMID 24605111, 2014). "Several studies demonstrated that the frequency of CXCR5+CD4+ T cells was not significantly increased in patients with autoimmune diseases, such as SLE, autoimmune thyroid disease, and juvenile dermatomyositis, compared to healthy controls." (PMID 24655429, 2014). "The CD4+CD25+ T cells show immune regulatory functions both in vitro and in vivo, as they can inhibit the autoimmune diseases and may participate in the induction of transplantation tolerance." (PMID 25548591, 2014). "Constitutive ablation of TGF-β signalling during thymic development of αβT cells (CD4-Cre or Lck-Cre–mediated) but not during peripheral life (dLck-Cre–mediated) invariably results in a generalised and rapidly lethal autoimmune disorder." (PMID 24115907, 2013). "A recent study showed that elevated sodium chloride concentration promoted the differentiation of CD4+ T cells into TH17 cells in vitro, and a high-salt diet accelerated the development of autoimmune disease through the activation of TH17 cells in a mouse model." (PMID 24354674, 2013). "This in turn could influence the function of the CD4+CD25+ Tregs and eventually, promote the development of autoimmune disorders." (PMID 24154763, 2013). "CD4+NKG2D+ T cells have been seen in chronic viral infections, as well as in autoimmune disorders, in which these cells may intensify the clinical manifestations after TCR and NKG2D engagement." (PMID 23947399, 2013). "Taken together, these results indicate that γδ T cells and CD4+CD25+Tregs have mutual regulatory effect on each other, which may play a part in the pathogenesis of different autoimmune diseases under specific microenvironments." (PMID 23533458, 2013). "In addition to CD4+ TReg, CD8+ suppressive T cells have been found playing an important role in the regulation of autoimmune disease." (PMID 22481922, 2012). "Here we have used pik3cg−/− mice, which lack expression of p110γ, and a highly selective PI3Kγ inhibitor to conduct a detailed investigation of the role of this protein in CNS autoimmune disease and we show that PI3Kγ plays a critical role in EAE by controlling CD4+ T cell activation and survival." (PMID 23028778, 2012). "However, our study demonstrated that after IFN-â treatment, the percentage of CD4+CCR4+ significantly increased in the NMO group, suggesting up-modulation of the Th2 response by IFN-â in autoimmune diseases involving the humoral immune system." (PMID 23202893, 2012).
autoimmune disease (continued). "Although Th2 cells and FoxP3+ Tregs have been reported to be critical for maintaining immune tolerance in autoimmune diseases, no significant increase of IL-4-producing or FoxP3 expression CD4+ cells was found in MOG35-55/I-Ab dimer-treated mice." (PMID 23077616, 2012). "T lymphocyte abnormalities were present in almost 20% of CVIDs patients and the majority of patients with decreased numbers of CD3, CD4 and CD8 positive T cells had been diagnosed with one or more complication, most often lymphoproliferative and autoimmune diseases." (PMID 22526591, 2012). "Several studies emphasized potential therapeutic roles for CD4+ and CD8+ Tregs in autoimmune diseases (such as experimental autoimmune encephalomyelitis, Rheumatoid arthritis, lupus, and diabetes mellitus type 1), pulmonary inflammation, transplantation, and inflammatory bowel disease." (PMID 23133648, 2012). "NKG2D expression is normally absent from CD4+ T-cells, however subsets of NKG2D+ CD4+ T-cells have been found in certain autoimmune diseases." (PMID 22870231, 2012). "The CD4+ CD25+ regulatory population of T cells (Treg cells), which expresses the forkhead family transcription factor (Foxp3), is the key component of the peripheral tolerance mechanism that protects against a variety of autoimmune diseases." (PMID 21162738, 2010). "Given the critical roles of CD4+ T cells and CD20+ B cells in autoimmune disease pathology, monitoring dynamic changes in these cell populations may provide insights into disease progression." (PMID 19693272, 2009). "In the periphery of young mice not prone to autoimmune disease, Tregs constitute a stable 10% of CD4+ T cells." (PMID 19543397, 2009). "CD4+CD25+FOXP3+ regulatory T cells (Treg) are of critical importance for the maintenance of immune homeostasis, as numerous experimental mouse models for autoimmune diseases correlate the presence of functional Tregs with amelioration of disease severity." (PMID 19779623, 2009). "Organ-specific autoimmune diseases, such as multiple sclerosis (MS) and itsanimal model, are mediated by IFN-γ and/or IL-17 producing CD4 T helper cells.Since PPAR-α regulates inflammation and cytokineproduction, PPAR-α agonists have been tested as apotential treatment for autoimmune diseases." (PMID 18645614, 2008). "Indeed, the introduction of T regulatory cells, characterized as CD4+CD25+, has been shown to alleviate autoimmune disease in various experimental models, such as EAE." (PMID 18773086, 2008). "We are not aware of any established clinical trials in autoimmune diseases, although CD4+CD25high regulatory T cell therapy will possibly be initiated in type 1 diabetes in the near future." (PMID 19046457, 2008). "CD4+CD25+ regulatory T cells are critical for the regulation of host tolerance and are considered to have enormous potential for suppressing pathological immune responses in autoimmune disease, transplantation, and graft-versus-host disease (GVHD)." (PMID 17284325, 2007). "For example, when CD4+ T cells isolated from peripheral lymphoid tissues of normal mice are depleted of CD4+CD25+ T cells and injected into nu/nu mice, the recipients develop a high incidence of organ-specific autoimmune disease." (PMID 15743488, 2005). "Because for many human autoimmune diseases the exact antigens recognized by these cells are not known, a therapy would be favorable that specifically targets the auto-aggressive CD4+ T cells and does not depend on the definition of the crucial auto-antigen." (PMID 15899047, 2005). "al, where adoptive transfer of CD4+CD25+ but not CD4+CD25- T cells could prevent autoimmune disease in athymic mice." (PMID 41256853, 2025). "However, the pathogenesis of many autoimmune diseases is not solely B-cell driven but heavily dependent on T cells—especially CD4+ helper T cells reactive to the same autoantigens." (PMID 40873568, 2025).
autoimmune disease (continued). "KIM‐1, also known as T cell immunoglobulin and mucin domain 1 (TIM‐1), is expressed on CD4 (+) T cells, plays an important role in regulating the Th2 reaction, and is involved in hepatitis A virus (HAV) autoimmunity, immune tolerance, atopic diseases, and other autoimmune diseases." (PMID 40365941, 2025). "Consistent with this idea, we found that sorted Btla−/− CD4 but not CD8 T cells could generate multi-organ autoimmune disease, and disease development did not occur in MHC class II-deficient recipients." (PMID 39471840, 2024). "Given autoimmune diseases’ nature, involving misidentification and overactivation of self-antigens, we identified differential clone types between GO and GH, highlighting unique TCR clone epitopes that emerge as GO progresses, primarily within CD4 CTL and CD8 effector T cell 1 (Te1) cells." (PMID 39365735, 2024). "RTE lacking BTLA caused a CD4 T cell and MHC class II dependent multi-organ autoimmune disease." (PMID 39471840, 2024). "Since KIR+ CD8 T cells from healthy donors and patients with distinct autoimmune disease could be grouped together based on the similarity of their expressed TCR repertoire, these cells may recognize common antigens expressed by CD4 cells that are activated by particular pathological conditions." (PMID 37934601, 2024). "In addition, human CD4+ T cells, similarly to mouse CD4+ T lymphocytes, generally do not express NKG2D, but the upregulation of NKG2D expression has been observed in T cell subsets in patients with certain autoimmune diseases." (PMID 38139373, 2023). "Bystander activation of CD4+ T cells and the role of antigen unrelated CD4+ T cells in various infections might lead to the development of autoimmune diseases, but the mechanisms involved have not been identified." (PMID 38032740, 2023). "In the context of CD4+ T cell differentiation in autoimmune diseases, such as inflammatory bowel disease and experimental autoimmune encephalomyelitis, TCF1+ CD4+ T cells were quiescent and could replenish TCF1- CD4+ T cells, which display effector functions in pathogenesis." (PMID 37737221, 2023). "Circulating Tfh (cTfh) cells, contain long-lived memory cells characterized by CD4+CXCR5+CD45RA- in peripheral blood, are functionally similar to GC Tfh cells, can induce autoantibody production by B cells, and play an important role in the pathogenesis of autoimmune diseases including SLE." (PMID 36119056, 2022). "The involvement of CD4 and CD8 T cells suggests that both class I and class II antigen presentation can trigger an autoimmune response, suggesting a much wider range of antigens may trigger autoimmune disease." (PMID 34867964, 2021). "Treg, a subset of CD4+ T cells that can balance Th cells and highly express CD25 and the unique transcription factor forkhead box P3 (FOXP3), has been demonstrated to play a crucial role in the maintenance of immune stability and occurrence and progression of autoimmune diseases." (PMID 35069594, 2021). "Conventional non-regulatory CD4 T cells contribute to the efficiency of many vaccines and are vital for the protection against many infections with bacteria, parasites, and fungi, but they can also mediate autoimmune diseases." (PMID 34910301, 2021). "Over the last decade, aberrant responses of T follicular helper (Tfh) cells, a subset of CD4 T cells which are able to localise predominantly in the B cell follicles through a high level of chemokine receptor CXCR5 expression, are described in pathogenesis of several autoimmune diseases." (PMID 34461933, 2021). "Interrogating the impact of sepsis on other autoimmune diseases, in particular those with different effector cells, rather than the CD4 T cells described here, could provide further robust characterization of the sepsis-induced immunoparalysis state." (PMID 33191915, 2020).
autoimmune disease (continued). "CD4+ CTLs were not only observed when infected with viruses, including human immunodeficiency virus (HIV) and cytomegalovirus (CMV), but also were found at the site of inflammation of several autoimmune diseases, such as RA, IgG4-related disease, and systemic sclerosis." (PMID 33603736, 2020). "Indeed CD4+CD25−FOXP3+ and CD4+CD45RA−FOXP3low populations increase in inflamed tissue of patients with autoimmune diseases and this has been attributed to self-reactive non-Treg cell responses." (PMID 33194927, 2020). "IL-21 and IL-6 together could induce CD4+CXCR+PD-1+ Tfh cell differentiation, and this Tfh cells could promote immunoglobulin production form B cells, thus Tfh cells could be a therapeutic target for treatment of autoimmune disease." (PMID 30760702, 2019). "miR-142-5p expression is downregulated in CD4+ T cells from patients with the multisystem autoimmune disease systemic lupus erythematosus (SLE) compared with healthy controls and overexpressed in an animal model of multiple sclerosis, suggesting that miR-142 plays a role in autoimmune disease." (PMID 30741720, 2019). "Furthermore, clustering analysis of the top 50 DMS across all samples in CD4+ cells also demonstrated that there is no significant distinction among the methylation signatures of these autoimmune diseases, while different from control individuals." (PMID 31024609, 2019). "It is not clear whether decreased CD4+T cell number and CD4/CD8 ratio relate to the nature of the autoimmune disease or the immunosuppressive agents." (PMID 30994732, 2019). "Here, we hypothesized that antigen non-related CD4+ T cells contribute to autoimmune disease pathogenesis in response to pro-inflammatory cytokines." (PMID 30755603, 2019). "CD4+ T helper (Th) cells that express the gut homing chemokine receptor CCR9 are increased in the peripheral blood of patients with inflammatory bowel disease and Sjögren's syndrome and in the inflamed lesions of autoimmune diseases that affect the accessory organs of the digestive system." (PMID 30662436, 2018). "STAT3 in CD4+ T cells was the top predicted transcription factor common for both resulting lists (Supplementary Datas 6, 7) and thus may regulate the pathogenicity of human TH17 cells in autoimmune diseases." (PMID 29150604, 2017). "Besides, we did not demonstrate that miR-4443 seems specific to GD because we did not investigate the miR4443 expression in CD4+ T cells from patients with other autoimmune disease." (PMID 29163513, 2017). "Indeed, T-cell development (in the thymus)—especially the deletion of self-reactive T cells and the production of regulatory T cells (CD4+CD25+ regulatory T cells, Tregs) that keep autoimmunity at bay—is one of the processes that clearly has a direct influence on autoimmune disease conditioning." (PMID 27534821, 2016). "These FoxP3+CD4+ Treg cell subsets are non-functional in male scurfy mice and boys with the multi-organ autoimmune disease immune-dysregulation polyendocrinopathy enteropathy X-linked syndrome (IPEX), due to loss-of-function mutations in the X-linked rodent Foxp3 and human FOXP3 genes, respectively." (PMID 25852682, 2015). "Recent evidence indicates that CD4 Th17 and CD8 T cells can contribute to tissue damage in some inflammatory and autoimmune diseases and could be targets for therapeutic intervention in some autoimmune diseases." (PMID 25024726, 2014). "We suggest that antibodies that block these pathways may have therapeutic benefit in human autoimmune diseases mediated by CD4 T cells without compromising resistance to infection." (PMID 24782861, 2014). "We believe that in vitro expanded autologous/heterologous Tregs may help treat autoimmune diseases, including SLE, and that CD4+CD25low/-GITR+ cells are interesting from this point of view, because they appear to be a homeostatic attempt to counteract the disease." (PMID 25256257, 2014).